TNF (tumor necrosis factor)
Diseases named in the same sentence as TNF in open-access papers (continued):
Sharing a sentence is not in itself a finding about the gene and the disease.
rheumatoid arthritis (continued). "To further verify the expression of LOXL1 in rheumatoid arthritis synovium, we used TNF-α to stimulate human osteosarcoma synovial cells for 48 h, extracted total protein and total mRNA, and detected the expression of LOXL1, INOS, COX2, and IL-6 in them through RT-qPCR and western blot." (PMID 38217541, 2024). "Moreover, TNF-α induces osteoclast differentiation in several diseases, such as rheumatoid arthritis, tooth movement, and periodontitis." (PMID 38238696, 2024). "Interestingly, unlike gypenoside III, rutin significantly improves inflammatory cell infiltration, cartilage and bone erosion, and synovial hyperplasia in rheumatoid arthritis models by lowering IL-1β and TNF-α and inhibiting the NF-κB pathway." (PMID 39273553, 2024). "Among pro-inflammatory mediators, interleukin (IL)- 1β, IL-6, IL-8, and Tumor Necrosis Factor (TNF)-α are the most prevalent during inflammation (e.g., inflammatory bowel disease and rheumatoid arthritis), thus representing appropriate targets for natural products." (PMID 39061865, 2024). "Compared with the Mock group, inflammation-related signaling pathways, including the IL-17 signaling pathway, TNF signaling pathway, NF-kappa B signaling pathway, rheumatoid arthritis, and viral protein interaction with cytokine and cytokine receptor, were enriched in the ASFV group." (PMID 39201769, 2024). "For example, when TNF-α inhibitors were used to treat patients with chronic inflammatory diseases, such as rheumatoid arthritis and Crohn’s disease, it reflected in serious cardiovascular complications with adverse outcomes, although the incidence was very rare." (PMID 38611112, 2024). "TACE, also known as ADAM17, plays a crucial role in the inflammatory response by converting pro-TNF-α to its active soluble form and cleaving other inflammatory mediators, making it a promising target for therapeutic intervention in diseases such as rheumatoid arthritis." (PMID 39729480, 2024). "Additionally, both invasive and transcutaneous devices have shown some success in treating inflammatory conditions, like rheumatoid arthritis, by reducing mouse and human serum levels of TNF, IL-6, and IL-1β." (PMID 39881804, 2024). "Synovial inflammation plays a central role in the development of rheumatoid arthritis, and its inflammatory milieu is regulated by a complex network of cytokines and chemokines, including tumor necrosis factor, interleukin 6, and possibly granulocyte colony-stimulating factor." (PMID 38217541, 2024). "In rheumatoid arthritis (RA), in vivo studies have reported immunosuppressive properties of EVs that inhibit the proliferation of T lymphocytes and reduction in pro-inflammatory cytokines IL-6, TNF-α, and IL-1β." (PMID 38397121, 2024). "How does the risk of incident cancer differ with the use of tumor necrosis factor inhibitors (TNFis), non-TNFis, or Janus kinase inhibitors (JAKis) in a US population of patients with rheumatoid arthritis?" (PMID 39565623, 2024). "The KEGG analysis revealed the significant enrichment of prognostic genes in the following pathways: IL‐17 signalling pathway, C‐type lectin receptor signalling pathway, TNF signalling pathway, Leishmaniasis, Rheumatoid arthritis and NF‐kappa B signalling pathway." (PMID 38363001, 2024). "By inhibiting TNF-activity, adalimumab, a human mAb, is a biological therapy to reduce symptoms and delay the onset of structural damage in patients with moderate to severe rheumatoid arthritis." (PMID 39407875, 2024). "This action is also related to the effect of BA on TNF-α synthesis, because available data indicate that PDE inhibitors are also anti-TNF-α agents used, among others, in the treatment of asthma, atopic dermatitis, chronic obstructive pulmonary disease, and rheumatoid arthritis." (PMID 39768006, 2024). "Inhibitors of TNF-α are used to treat rheumatoid arthritis and are blockers of TNFR1 and TNFR2." (PMID 39088270, 2024).
rheumatoid arthritis (continued). "As a result, medications inhibiting TNF-α, such as infliximab and adalimumab, have proven effective in the treatment of immune-related conditions, including ankylosing spondylitis, inflammatory bowel diseases, psoriasis, and rheumatoid arthritis (RA)." (PMID 38392902, 2024). "The ER stress response could be stimulated by the high expression of the pro-inflammatory element TNFα in the microenvironment of rheumatoid arthritis (RA)." (PMID 39695085, 2024). "Likewise, it is known that TNF-α is one of the cytokines that perpetuates the inflammatory response, for example, in rheumatoid arthritis, by activating the synthesis of other cytokines such as IL-6." (PMID 39861663, 2024). "Dysregulated signaling through TNF receptor 1 (TNFR1) and the production of TNFα may lead to the development of rheumatoid arthritis, inflammatory bowel disease, and psoriasis." (PMID 37885900, 2023). "TNFα plays an important role in chronic inflammatory diseases, such as rheumatoid arthritis (RA)." (PMID 37894425, 2023). "Seven hub genes IL10, IL4, IL6, IFNG, IL1B, TNF and IL17A might be responsible for causing Colitis and Arthritis, except for Rheumatoid Arthritis." (PMID 36989283, 2023). "Additionally, TNF-α is up-regulated in collagen and aggrecan cartilage destruction in joints affected by rheumatoid arthritis and is responsible for necroptosis in injured and inflamed tissue." (PMID 37443993, 2023). "The CLL patients also have high levels of serum TNF, much of it coming from lymphocytes, and patients undergoing anti-TNF treatment, such as for rheumatoid arthritis and inflammatory bowel disease have a significantly higher risk of developing lymphomas than normal individuals." (PMID 36997529, 2023). "When TNF-α is dysfunctional, diverse immunopathology can result, including rheumatoid arthritis, inflammatory bowel disease, Wegener granulomatosis, sarcoidosis, psoriasis, psoriatic arthritis, ankylosing spondylitis, juvenile chronic arthritis, atherosclerosis, and sepsis." (PMID 37180165, 2023). "Studies of rheumatoid arthritis patients using a small sample size have shown that the biologic concentrations in breast milk are very low or even undetectable in patients, thus TNF inhibitors may still be considered in patients during lactation." (PMID 37485474, 2023). "Similarly, IL-32β overexpressing mice showed reduced levels of proinflammatory cytokines TNF-α, IL-6, and IL-1β in a murine model of rheumatoid arthritis, which improved arthritic inflammation in these mice." (PMID 37727785, 2023). "TNFα plays key functions in the maintenance of homeostasis and disease pathogenesis, and therapeutic strategies targeting TNFα were shown to provide efficient treatment of inflammatory diseases such as rheumatoid arthritis (RA) and inflammatory bowel diseases (IBD)." (PMID 36829432, 2023). "Similarly, atorvastatin revealed a potential immunomodulatory effect against rheumatoid arthritis by reducing IL-17A, TNF, and IL-6 levels." (PMID 38105357, 2023). "TNF-α was the first cytokine to be validated as a therapeutic target for rheumatoid arthritis." (PMID 36814288, 2023). "Interestingly, similar effects were observed in synoviocytes derived from patients affected by rheumatoid arthritis and co-stimulated with HQ and TNF-alpha." (PMID 36899825, 2023). "Furthermore, rheumatoid arthritis patients taking anti-TNF medications were shown to have a lower hospitalization rate even if they caught COVID-19." (PMID 37047115, 2023). "TNF-α, IL-1β, and IL-6 are potent pro-inflammatory cytokines exerting pleiotropic effects on various cell types and play a critical role in the pathogenesis of chronic inflammatory diseases, such as OA and rheumatoid arthritis (RA)." (PMID 36846635, 2023). "It was hypothesized that bLF treatment might help stop the pathologic growth of rheumatoid arthritis because TNF is crucial for beginning and advancing inflammation and bone destruction, including periodontitis." (PMID 38152780, 2023).
rheumatoid arthritis (continued). "Furthermore, anti-TNF therapy has been shown to promote the expansion of regulatory T cells by paradoxically promoting the binding of membrane TNF-TNF-RII in rheumatoid arthritis." (PMID 37608254, 2023). "KEGG enrichment analysis of common targets showed that the regulation effect of Jinwujiangu prescription on RA was related to TNF signaling pathway, rheumatoid arthritis, IL-17 signaling pathway, NF-kappa B signaling pathway, and Toll-like receptor signaling pathway." (PMID 36816744, 2023). "In rheumatoid arthritis, a high baseline frequency of circulating Th17 cells has been associated with a lack of response to TNF-α inhibitors." (PMID 37047086, 2023). "In addition, the therapeutic guidelines for rheumatoid arthritis and psoriatic arthritis recommend anti-TNF as the initial biologic treatment." (PMID 37297665, 2023). "However, excessive and prolonged production of TNF-α can have detrimental effects, such as inducing joint destruction in patients with rheumatoid arthritis." (PMID 38032288, 2023). "Macrophages, T cells, and B cells in rheumatoid arthritis are all major producers of TNF." (PMID 37301964, 2023). "Interestingly, DHM has been found to effectively relieve rheumatoid arthritis symptoms and mitigate the release of inflammatory mediators as TNF-α and interleukins through activation of the Nrf2/HO-1 pathway." (PMID 37111238, 2023). "In contrast, several immune-related KEGG pathways were enriched in stage III tumors, including TNF signaling (P = 0.017), cytokine receptor interaction (P = 0.02), IL-17 signaling (P = 0.015), Epstein-Barr virus infection (P = 0.025), and rheumatoid arthritis (P = 0.024)." (PMID 35881197, 2023). "Recently, an orally active, small-molecule TNF inhibitor (TNF-inhibitory molecule 1, TIM1) was found to be effective for treatment of rheumatoid arthritis and other TNF-dependent systemic disorders of inflammation, and TIM1 seems to be useful in cancer treatment." (PMID 37097392, 2023). "Moreover, attenuated TNF-α production has been shown after IL-6 treatment in plasmacytoid dendritic cells in rheumatoid arthritis." (PMID 37908302, 2023). "Although the use of TNFα inhibitors to treat rheumatoid arthritis is more common among the South African doctors surveyed, accounting for about half of the prescriptions, it can be seen from this study that the number of reported adverse events in Africa is still very low." (PMID 37554981, 2023). "Moreover, another study reports that lower PCSK9 at baseline and at 12 months after TNF inhibitor therapy is related to better response in rheumatoid arthritis (RA) patients." (PMID 37249282, 2023). "Module 2 comprises 73 genes that have been associated with various pathways, such as Ubiquitin mediated proteolysis, TNF signaling pathway, Rheumatoid arthritis, JAK–STAT signaling pathway, Cytokine-cytokine receptor interaction, and NF-kappa B signaling pathway." (PMID 37720481, 2023). "In addition, paradoxical HS responses have been recently reported in patients with rheumatoid arthritis or psoriatic arthritis (PsA) during long-term treatment with TNF inhibitors, tocilizumab or rituximab." (PMID 37484864, 2023). "A recent publication described the development of bispecific nanobodies targeting IL-6 and TNF with additive efficacy in translational models of rheumatoid arthritis by inhibition of classic and trans-signaling of IL-6 and TNF signaling, a strategy that most likely will not work in IBD." (PMID 37838173, 2023). "While antagonism of TNFα with monoclonal antibodies yielded effective results in patients with rheumatoid arthritis and inflammatory bowel disease, clinical trials for anti-TNFα in patients with chronic heart failure (RECOVER and RENAISSANCE) were terminated prematurely due to no observable benefit." (PMID 37200978, 2023).
rheumatoid arthritis (continued). "For example, there was a higher risk of cancer in patients who took tofacitinib than an anti-tumor necrosis factor (TNF) agent after 18 months of therapy for rheumatoid arthritis, according to a post-hoc analysis of a randomized controlled trial (ORAL SURVEILLANCE)." (PMID 37190126, 2023). "Additionally, the use of TNF-α as a protein biomarker has been reported in several disease diagnoses, such as cancers, Alzheimer’s disease, rheumatoid arthritis, and diabetes-related eye diseases." (PMID 37047115, 2023). "Notably, the normalization of T-cell subsets has been observed in rheumatoid arthritis patients who have undergone long-term treatment with anti-TNF or IL-6R blocker therapies." (PMID 37608254, 2023). "TNF is reported to mediate a broad range of inflammatory diseases and is a regulator of inflammation and inflammation-related diseases, such as inflammatory bowel disease, cardiovascular disease, and rheumatoid arthritis." (PMID 36635624, 2023). "Interestingly, results from previous studies have shown a similar inhibition of TNF in rheumatoid arthritis patients treated with VNS further strengthening our results." (PMID 36845140, 2023). "In patients with rheumatoid arthritis, circulating levels of cytokines, such as TNFα, are elevated." (PMID 36838809, 2023). "Anti-TNF-α therapies have been successfully introduced for the treatment of several autoimmune diseases, including rheumatoid arthritis and Crohn’s disease, possibly suggesting the role of the TNF-α-mediated ablation of tolerogenic cDCs in these autoimmune responses." (PMID 37237529, 2023). "In a phase 3 clinical trial (NCT05428488), the level of rheumatoid arthritis remission in the group treated with TNF-α inhibitors is a reference to the efficiency of treatment consisting of abatacept, which is a soluble cytotoxic T lymphocyte antigen 4 (CTLA-4)." (PMID 36969193, 2023). "Some data in the literature suggest that epigenetic changes through regulating pro-inflammatory responses via NFkB affecting TNF-α may be significantly involved in the pathogenesis of rheumatoid arthritis and other chronic inflammatory diseases." (PMID 36671633, 2023). "For example, patients with rheumatoid arthritis and Crohn’s disease are effectively treated with various TNF-blocking monoclonal antibodies, while a human IL-12/IL-23 monoclonal antibody is used to treat psoriasis patients, both resulting in reduced neutrophil infiltration into affected tissues." (PMID 37566060, 2023). "In addition, macrophages from rheumatoid arthritis (RA) patients expressed tumor necrosis factor (TNF), which inhibited PTEN-induced putative kinase 1 (PINK1)-mediated mitophagy and altered mitochondrial function to elevate cytosolic mtDNA levels." (PMID 38036728, 2023). "Furthermore, during early rheumatoid arthritis (RA), several cohort studies revealed that remission rates were lower for females than males treated with TNF-inhibitor therapies." (PMID 36831165, 2023). "Indeed, in our meta-analyses, the six studies that compared tofacitinib to anti-TNF agents all enrolled patients with a mean age around 50 years who had rheumatoid arthritis (with the exception of one study of psoriatic arthritis)." (PMID 37190126, 2023). "For this reason and because the majority of approved biosimilars are TNF inhibitors used to treat patients with inflammatory conditions, patients with rheumatoid arthritis, plaque psoriasis, Crohn disease, and ulcerative colitis were more frequently enrolled (38 STPs)." (PMID 37788264, 2023). "Furthermore, several nanobodies specific for VEGF have been reported, and very recently (Sept/2022) a trivalent anti-TNF nanobody called ozoralizumab was approved in Japan for the treatment of rheumatoid arthritis." (PMID 37175117, 2023). "Increased levels of IL-4, IL-6, TNF-α, IL-10, and IL-17 have been reported in rheumatoid arthritis." (PMID 37111383, 2023).
rheumatoid arthritis (continued). "Some studies have suggested that treating rheumatoid arthritis (RA) with TNF inhibitors not only alleviates joint inflammation and damage but might also improve periodontal disease outcomes." (PMID 36845132, 2023). "TNF-α has been shown to be involved in the pathogenesis of several immune-mediated diseases including rheumatoid arthritis (RA), ankylosing spondylitis (AS), juvenile idiopathic arthritis (JIA), psoriatic arthritis (PsA), psoriasis, and inflammatory bowel diseases (IBD)." (PMID 37629636, 2023). "Several markers of systemic inflammation may be impacted by age, most notably TNF- α, which has been directly assessed and is increased in inflammatory pathologies such as rheumatoid arthritis and inflammatory bowel disease." (PMID 36144256, 2022). "Various conditions, such as denervation, disuse, aging, rheumatoid arthritis (RA), Crohn’s disease, and cachexia, can cause muscle atrophy, which are all characterized by elevated levels of circulating pro-inflammatory mediators in patients, such as TNFα, IL-1β, and/or IL-6." (PMID 36618945, 2022). "The latest research showed that Z. rhetza, a spice similar to andaliman, exerted anti-inflammatory activity for treating rheumatoid arthritis and osteoarthritis by inhibiting the gene expression of TNF-α and prostaglandin E2 (PGE2), which are related to in vitro inflammation." (PMID 36429168, 2022). "Besides the COPD, the patient was known for a rheumatoid arthritis, which was treated with methotrexate (20 mg/week) and infliximab (TNF-α inhibitor; 300 mg every ten weeks)." (PMID 36104715, 2022). "The factors influencing long-term responses to a tumor necrosis factor inhibitor (TNFi) in rheumatoid arthritis (RA) patients currently remain unknown." (PMID 35734167, 2022). "In addition, 184 pathways were contained in KEGG pathway enrichment analysis, mainly including TNF signaling pathway, IL-17 signaling pathway, Rheumatoid arthritis, Cytokine-cytokine receptor interaction, Th17 cell differentiation." (PMID 34997010, 2022). "In rheumatoid arthritis, it downregulates the PI3K/AKT pathway to modulate the proinflammatory responses of associated macrophages, altering the production of IL-6, IL-8 and TNF-α." (PMID 35562916, 2022). "Decreases TNF-α and IL-6 contents in the serum; prevents the synovial hyperplasia and inflammatory cell infiltration of the mouse ankle joint; and exerts a certain therapeutic effect on rheumatoid arthritis." (PMID 35566359, 2022). "Although the Food and Drug Administration (FDA) has licensed Anakinra for the treatment of rheumatoid arthritis in certain individuals, it is only moderately effective and inferior to TNF-α inhibitors, showing its limited application (Ramírez and Cañete 2018)." (PMID 36387275, 2022). "TNF-α, IL-1β, and IL-6 are mainly involved in acute inflammation, leading to healing, trigger removal, tissue repair, and some systemic autoimmune diseases such as rheumatoid arthritis." (PMID 36613927, 2022). "TNF can activate the immune system, but inappropriate or excessive production of TNF may be harmful and lead to rheumatoid arthritis, inflammatory bowel disease, psoriasis arthritis, psoriasis, and non-infectious uveitis." (PMID 36544491, 2022). "This is the first study in the Middle East and North Africa where the effect of TNF inhibitors on weight gain in a specific group of patients (only seropositive rheumatoid arthritis) has been studied, and this result was compared and correlated with non-TNF therapy and disease activity." (PMID 35784983, 2022). "In the present study, when synovial fibroblasts from patients with rheumatoid arthritis were treated with TNF-α, we investigated whether mitophagy was induced in RASFs." (PMID 35628458, 2022). "Additionally, treatment with non-selective adrenergic antagonist carvedilol suppresses pro-inflammatory cytokines TNF-α in a complete Freund’s adjuvant-induced rat rheumatoid arthritis model." (PMID 35893792, 2022).